AQP4 (aquaporin 4)
Diseases named in the same sentence as AQP4 in open-access papers (continued):
Sharing a sentence is not in itself a finding about the gene and the disease.
optic neuritis (268 papers, 2008 to 2026). Optic neuritis is inflammation of the optic nerve, the nerve that carries the visual signal from the eye to the brain.The conditionmay cause sudden, reduced vision in the affected eye(s). "The novel rat model using a patient serum-soaked ON sponge reliably produced localized optic neuritis characterized by AQP4 loss, astrocyte activation, demyelination, and RGC degeneration, closely mimicking human NMOSD lesions." (PMID 41227356, 2025). "In pursuit of peripheral blood transcriptomic markers significantly associated with AQP4 positive optic neuritis, a phenotypic correlation analysis was conducted on the gene modules identified in the preceding analysis." (PMID 39238786, 2024). "Particularly, the brown module (MEbrown) demonstrated a close association with the phenotype of AQP4-positive optic neuritis." (PMID 39238786, 2024). "Several IMIDs linked to ON, such as aquaporin-4 antibody-associated optic neuritis (AQP4-ON), myelin oligodendrocyte glycoprotein antibody-associated optic neuritis (MOG-ON), and neuro-sarcoidosis, show remarkable response to corticosteroid treatment." (PMID 38867071, 2024). "AQP4-positive optic neuritis is associated with a decline in vision-related quality of life as well as an increased likelihood of experiencing depression." (PMID 37840923, 2023). "In summary, AQP4-positive optic neuritis was found to be significantly associated with impaired vision-related quality of life and an increased occurrence of depressive symptoms." (PMID 37840923, 2023). "In accordance with diagnostic criteria, all AQP4-Ab-seropositive patients had at least one core clinical characteristic (in this group we observed optic neuritis, acute myelitis or area postrema syndrome); alternative diagnosis was excluded." (PMID 35884693, 2022). "While optic neuritis from AQP4-IgG+NMOSD is known to cause more severe vision loss, some studies have shown similar amounts of thinning of the pRNFL and mGCIPL despite this discordant visual outcome." (PMID 35785363, 2022). "In AQP4 Ab-associated optic neuritis, optic nerve damage depends on the severity of each attack; conversely, the nerve injury associated with MOG Abs seems to be related mainly to the frequency of attacks." (PMID 34997443, 2022). "Severe thinning of these layers often occurs in MOGAD optic neuritis from recurrent attacks, while AQP4-IgG+NMOSD tends to cause significant thinning after single attacks." (PMID 35785363, 2022). "Neuromyelitis optica-associated optic neuritis was diagnosed with seropositive AQP4-Ab using cell-based assays (CBAs), and the fluctuation of antibody levels was tested using an enzyme-linked immunosorbent assay (ELISA) method throughout the follow-up period." (PMID 34017301, 2021). "NMOSD encompasses a group of syndromes typically characterized by optic neuritis and/or acute myelitis, often in association with serum IgG autoantibodies directed against aquaporin-4 (AQP4-IgG), an astrocytic water channel." (PMID 34354581, 2021). "Neuromyelitis optica-associated optic neuritis is diagnosed with a positive serum aquaporin-4 antibody (AQP4-Ab), which targets the astrocytic water channel in the central nervous system (CNS)." (PMID 34017301, 2021). "The spectrum of NMO therefore refers to clinical pictures in which the positivity of AQP4-IgG is associated with other clinical pictures besides optic neuritis and myelitis such as diencephalic, brainstem or other cerebral syndromes." (PMID 32722601, 2020). "The presence of AQP4 Ab probably plays a critical role in retinal ganglion cell loss in optic neuritis." (PMID 28199381, 2017). "It has been suggested that antibody testing for AQP4-IgG be reserved to patients with severe visual loss, poor visual recovery, bilateral or sequential visual involvement, recurrent optic neuritis and unique findings on the MRI of the orbits." (PMID 29064441, 2017).
optic neuritis (continued). "Optic neuritis (ON) in patients with anti-myelin oligodendrocyte glycoprotein (MOG)-IgG antibodies has been associated with a better clinical outcome than anti-aquaporin 4 (AQP4)- IgG ON." (PMID 28125740, 2017). "Some patients with anti-AQP4 antibody had recurrent optic neuritis, recurrent myelitis, optic neuritis and myelitis associated with systemic autoimmune disease or the brain lesions, rather than the typical features of optic neuritis and LESCLs." (PMID 25433369, 2014). "Serum anti-Aqp-4 antibodies should be part of the diagnostic workup of patients with active TB who present with transverse myelitis and/or optic neuritis." (PMID 25169022, 2014). "Optic neuritis associated with anti-AQP4-Ab affected only females who had bilateral eye involvement, and all had severe visual impairment in the acute phase and delayed partial visual recovery." (PMID 21744285, 2011). "NMO is an autoimmune disease characterized by severe optic neuritis and transverse myelitis where serum from patients is enriched with anti-AQP4 antibodies leading to loss of AQP4 in the active perivascular NMO lesions." (PMID 18836575, 2008). "However, the molecular mechanisms underlying the disease, particularly AQP4-associated optic neuritis (AQP4-ON), remain to be fully elucidated." (PMID 39238786, 2024). "The presence of AQP4 in the first episode of TM may indicate the risk of recurrence and the development of optic neuritis within less than a year." (PMID 37601991, 2023). "Overall, outcome is generally better in MOG-associated than in AQP4-associated optic neuritis." (PMID 34997443, 2022). "Moreover, a recent study showed that Japanese NMOSD patients with AQP4-IgG had a lower risk of relapse, especially transverse myelitis and optic neuritis attacks, compared with Caucasian patients." (PMID 33436735, 2021). "Some pathological features observed in longitudinally extensive myelitis and optic neuritis lesions may be associated with glutamatergic excitotoxicity since the AQP4-IgG/AQP4 complex downregulates the main astrocytic glutamate transporter EAAT2." (PMID 31031597, 2019). "In addition, AQP4-Ab positive optic neuritis is characterized by a higher risk of relapse." (PMID 39470886, 2025). "Case 1 involved a 69-year-old male who developed stroke-like symptoms after surgery for gastric cardia cancer, which later progressed to optic neuritis, confirmed by positive aquaporin-4 (AQP4) antibodies in both serum and cerebrospinal fluid." (PMID 42318482, 2026). "Patients diagnosed with anti-aquaporin 4 antibody (AQP4-Ab) positive optic neuritis and had been initiated on biologics (satralizumab, eculizumab, and inebilizumab) between January 2020 and August 2022 were identified at 30 facilities in Japan." (PMID 39470886, 2025). "The positive anti-AQP4 antibody, optic neuritis, acute myelitis, and the lesion in the area postrema met the diagnostic criteria for NMOSD." (PMID 40018473, 2025). "Given the positive anti-AQP4 antibody results, along with the presence of optic neuritis, a lesion in the area postrema, and acute myelitis, a diagnosis of NMOSD was made." (PMID 40018473, 2025). "NMO and NMOSD are autoimmune conditions of the central nervous system characterized by recurrent episodes of optic neuritis and LETM, often associated with anti-AQP4 antibodies." (PMID 40995295, 2025). "The patient was positive for anti-AQP4 antibody and also exhibited optic neuritis, acute myelitis, and area postrema syndrome, leading to the diagnosis of NMOSD." (PMID 40018473, 2025). "Although MOGAD and AQP4-positive NMOSD can present with overlapping features such as optic neuritis and longitudinally extensive myelitis, they represent distinct autoimmune disorders with important diagnostic and therapeutic implications." (PMID 41583138, 2025).
optic neuritis (continued). "Because visual function of AQP4-Ab positive optic neuritis is getting worse at each relapse, effective treatment that prevents relapse is extremely important in the chronic phase of AQP4-Ab positive optic neuritis." (PMID 39470886, 2025). "In NMOSD patients, the positive rate of AQP4 antibodies was determined to be 81.8%, and the clinical subtypes included optic neuritis (ON, 21.2%), myelitis (TM, 34.8%), and optic neuromyelitis (ON+TM, 43.9%)." (PMID 41474776, 2025). "In NMO-driven optic neuritis, we are unaware of work specifically detailing the plasma cell presence in the optic nerve; however, it is well established that AQP4-specific antibody, B cells, and plasma cells are present in NMO patient CSF." (PMID 41583430, 2025). "The clinical characteristics of AQP4-Ab positive optic neuritis have been elucidated by an epidemiological study of refractory optic neuritis in Japan." (PMID 39470886, 2025). "Persistent AQP4-IgG seropositivity (titer 1:32) was noted, and gadolinium-enhanced MRI revealed focal signal abnormalities in the bilateral optic nerves, confirming optic neuritis." (PMID 40491913, 2025). "In conclusion, this study detected retinal damage in aquaporin-4 seropositive optic neuritis patients by optical coherence tomography, and estimated the sample size for two-sample parallel designed clinical trials using two methods." (PMID 38633413, 2024). "The first attack of AQP4-IgG seropositive NMOSD are most commonly optic neuritis (45%) and myelitis (47%), followed by APS (9.4-14%), only a small number of patients presenting with isolated brainstem, brain or diencephalon damage." (PMID 38773402, 2024). "The aquaporin-4 channels that drive glymphatic flow are affected by specific antibodies in neuromyelitis optical-spectrum diseases including bilateral optic neuritis and spinal cord myelitis, presenting yet another target for the present methods." (PMID 38278832, 2024). "Distinct AQP4-IgG serotypes are found within the CSF, and optic neuritis can be induced in mouse models when AQP4-IgG and complement are repeatedly injected in the cisterna magna." (PMID 38178155, 2024). "In contrast, MOG antibody-related optic neuritis is typically localized to the anterior part of the optic nerve and exhibits more pronounced inflammation compared to AQP4-IgG-positive cases." (PMID 39618752, 2024). "We thus filtered genes that occupy central positions within the network and are closely related to the disease type, in an attempt to uncover unique key molecules and biological processes involved in the pathogenesis of AQP4-positive optic neuritis." (PMID 39238786, 2024). "Conversely, a high proportion of eyes (29%) developed MME among patients with anti-aquaporin-4 antibody-positive optic neuritis, but the prevalence of this etiology of OA was very low in our cohort (n = 7 out of 643 [1%] eyes)." (PMID 39311320, 2024). "We recruited four aquaporin-4 seropositive optic neuritis patients (five eyes) who received glucocorticoid treatment and underwent optical coherence tomography examination." (PMID 38633413, 2024). "In the brain, AQP4 + NMOSD typically presents with bilateral optic neuritis affecting the chiasma and focal lesions in specific areas, including the area postrema, midbrain, and diencephalon." (PMID 38473365, 2024). "Subject 1 (AQP4-IgG + NMOSD) experienced an optic neuritis attack 1 month prior to the second SC scan (two optic neuritis attacks in total between visits)." (PMID 38343712, 2024). "It was observed that the brown module (MEbrown) demonstrated a significant correlation with the AQP4 positive optic neuritis phenotype and a positive correlation with the extent of post-onset visual acuity decline." (PMID 39238786, 2024). "The WGCNA analysis unveiled several gene modules significantly correlated with the clinical phenotypes of AQP4 positive optic neuritis." (PMID 39238786, 2024).
optic neuritis (continued). "Higher AQP4–IgG titers correlated with more severe attacks, including severe optic neuritis attacks." (PMID 39709432, 2024). "Over 80% of pSS patients who experience acute neurological events, such as myelitis or optic neuritis, have been reported to test positive for AQP4-IgG." (PMID 39055718, 2024). "In patients with AQP4-positive optic neuritis, visual acuity is worse and the retinal nerve fiber layer is thinner than in those with AQP4-negative optic neuritis." (PMID 37840923, 2023). "This clinical picture is labeled as atypical optic neuritis and should prompt serum testing for AQP4 and MOG antibodies." (PMID 37958968, 2023). "It is equally advisable to treat those patients aggressively, similarly to those with prototypical AQP4 optic neuritis." (PMID 37958968, 2023). "AQP4-IgG-positive NMOSD optic neuritis had a predominant optic-chiasm location, and brain lesions mainly affected hypothalamic regions and the postrema area (MOGAD versus AQP4-IgG-positive NMOSD,p= 0 .013)." (PMID 37379865, 2023). "Clinicians should assess vision-related QoL and depressive symptoms in patients with AQP4-positive optic neuritis to facilitate patient-centered care." (PMID 37840923, 2023). "There is reason to suspect that more severe retinal structural changes in AQP4-positive optic neuritis lead to substantial vision-related QoL losses." (PMID 37840923, 2023). "Aquaporin-4 (AQP4) antibody-seropositive optic neuritis (AQP4-ON) is one of the most common types of optic neuritis in China." (PMID 37840923, 2023). "Compared to those who did not develop visual disability, the disabled patients had a higher ratio of optic neuritis as the presentation of onset (p <0.001) and a higher proportion of AQP4-IgG seropositive (p=0.017)." (PMID 37350969, 2023). "More than 80% of pSS patients with acute neurological events such as myelitis or optic neuritis are reported to be AQP4-IgG positive." (PMID 36401063, 2023). "It is crucial for clinicians to assess both vision-related QoL and depression in patients with AQP4-positive optic neuritis to provide patient-centered care." (PMID 37840923, 2023). "This appears to have an axonal pattern of damage according to the OCT and Visual Evoked Potential (VEP) findings, hence the resemblance to AQP4 optic neuritis." (PMID 37958968, 2023). "We report a case of radiologically isolated longitudinally extensive optic neuritis in an asymptomatic 12-year-old female with positive serum AQP4-Ab, with resolution of imaging changes after immune therapy." (PMID 35332817, 2022). "The clinical features are considered to reflect a unique disease with a different etiology from MS and optic neuritis, related to aquaporin-4 (AQP-4)-IgG." (PMID 36648967, 2022). "The NMO-SD are defined, apart from optic neuritis and myelitis, by antibodies against aquaporin 4 (AQP4) and myelin oligodendrocyte glycoprotein (MOG)." (PMID 34226958, 2022). "The AQP4-IgG positive NMOSD patients presented with the clinical symptoms of optic neuritis (ON) and transverse myelitis (TM), whereas encephalitis symptoms were more prevalent in MOGAD patients." (PMID 35898513, 2022). "Optic neuritis (ON) is a common manifestation of aquaporin-4 (AQP4) antibody seropositive neuromyelitis optica (NMO)." (PMID 36303157, 2022). "Optical coherence tomography (OCT) is an essential part of the diagnostic evaluation of optic neuritis and this imaging diagnostic test can be useful for confirming an optic neuropathy as well as potentially discriminating between MOGAD, AQP4-IgG+NMOSD and MS." (PMID 35785363, 2022). "We present the case of a 65-year-old patient, admitted to our clinic with optical neuritis, followed up approximately 10 days later by cervical myelitis, who tested positive for both anti-AQP4 and anti-MOG antibodies." (PMID 36341113, 2022).
optic neuritis (continued). "Optic papillitis with ocular pain and retrobulbar type without ocular pain are more common in patients with anti-MOG antibody and AQP4 antibody, respectively, as compared to idiopathic optic neuritis." (PMID 34484845, 2021). "In MOG-ab-positive and AQP4-ab-positive children, maintenance therapy was a protective factor for recurrence, but presenting optic neuritis was a predictor of earlier relapse." (PMID 33841310, 2021). "Six months after natalizumab treatment, she developed optic neuritis attributed to the anti-AQP4 antibodies." (PMID 34693289, 2021). "The second patient developed optic neuritis six months after natalizumab treatment, most likely related to anti-AQP4 antibodies." (PMID 34693289, 2021). "These cases suggest possible association between minor trauma to the eyes and the subsequent occurrence of optic neuritis in patients with serum anti‐AQP4 antibodies." (PMID 33591639, 2021). "We positively detected serum AQP4-IgG in 23 (76.7%) patients, optic neuritis in 7 (23.3%) patients, myelitis in 16 (53.3%) patients, brain attacks in 3 (10%) patients, and mix attacks in 4 (13.3%) patients." (PMID 34531808, 2021). "Results indicated that serum anti-AQP4 antibodies were positively detected in 87 (85.9%) patients, optic neuritis in 22 (23.3%), myelitis in 48.54%, and brain attacks and mixed attacks in 34 (28.16%)." (PMID 34531808, 2021). "In patients with AQP4-IgG, the diagnosis only requires one of the six core clinical criteria including optic neuritis and acute myelitis." (PMID 33011853, 2021). "Both patients showing brainstem symptoms or isolated unilateral optic neuritis were positive for serum AQP4 antibody, and AQP4 antibodies have been proposed as a pathogenic and diagnostic biomarker for NMOSD." (PMID 33796134, 2021). "Up until a decade ago, patients with optic neuritis (ON) in China were primarily tested for aquaporin-4 antibodies (AQP4-Abs) due to its high specificity and sensitivity in diagnosing neuromyelitis optica (NMO)." (PMID 34272440, 2021). "Its clinical phenotypes differ but overlap with those of AQP4-antibody disease and include acute disseminated encephalomyelitis, brainstem and cerebral cortical encephalitis, as well as optic neuritis and myelitis." (PMID 32670177, 2020). "Our patient experienced four consecutive attacks of bilateral optic neuritis and acute myelitis, was AQP4‐IgG‐seropositive, and had a contiguous intramedullary lesion that met the international consensus diagnostic criteria for NMOSD." (PMID 32755074, 2020). "This cross-sectional study included 39 patients exclusively with aquaporin 4-IgG seropositive NMOSD of which 25 patients had a history of optic neuritis (NMOSD-ON) and 37 age- and sex-matched healthy controls (HC)." (PMID 32335748, 2020). "With respect to optic neuritis, anti-MOG seropositive patients are at lower risk of further relapses and have better visual field outcomes compared to anti-AQP4 seropositive patients." (PMID 33182495, 2020). "Up to 40% of patients with NMO, recurrent LETM or recurrent optic neuritis are anti-AQP4-seronegative upon disease onset and during the course of the disease and anti-AQP4 antibodies are present in the serum of 70–90% of patients with NMOSD." (PMID 33182495, 2020). "These 47 patients had typical MOG-IgG-associated clinical phenotypes such as optic neuritis, ADEM, myelitis, AQP4-seronegative NMOSD, or other demyelinating phenotypes reported to be associated with MOG-IgG." (PMID 32024795, 2020). "A recent epidemiologic survey in Japan revealed that of 531 cases of optic neuritis (ON), 23% tested positive for either anti-aquaporin-4 (AQP4) or anti-myelin oligodendrocyte glycoprotein (MOG) antibodies." (PMID 33628473, 2020). "Before transplant, 11 had clinical attacks of optic neuritis, 12 had myelitis, 1 had area postrema syndrome and 11 of 12 were AQP4-IgG-positive." (PMID 32722601, 2020).